NPSR1 (neuropeptide S receptor 1)
Diseases named in the same sentence as NPSR1 in open-access papers (continued):
Sharing a sentence is not in itself a finding about the gene and the disease.
Anxiety (31 papers, 2010 to 2025). Intense feelings of nervousness, tension, or panic often arise in response to interpersonal stresses. "The results revealed that individuals carrying both the S and T alleles of the 5-HTTLPR and NPSR1 polymorphisms exhibited a stronger FC response to anxiety-inducing context during the late acquisition phase." (PMID 37626553, 2023). "Human NPSR1 polymorphisms have been linked to panic disorder and anxiety, as well as asthma, endometriosis, and other inflammatory disorders." (PMID 36036349, 2022). "In conclusion, both the S and the T alleles of the 5HTTLPR and NPSR1 polymorphisms, seem to enhance the vulnerability to anxiety levels and/or anxiety disorders, but only the S allele influences differential cued fear conditioning." (PMID 23630477, 2013). "In contrast, anxiety ratings were only influenced by the NPSR1 polymorphism with AA carriers showing higher anxiety ratings in CXT+ as compared to CXT−." (PMID 23630477, 2013). "Human as well as animal research suggests that the T allele of the NPSR1 polymorphism and the S allele of the 5HTTLPR polymorphism are vulnerability factors for enhanced anxiety levels and anxiety disorders, presumably as a result of facilitated fear conditioning." (PMID 23630477, 2013). "The neuropeptide S (NPS) and its receptor (NPSR1) have been extensively studied over the last two decades for their roles in locomotion, arousal/wakefulness and anxiety-related and fear-related behaviours in rodents." (PMID 34451877, 2021). "The NPS/NPSR1 system was initially recognized as regulator of locomotion, arousal/wakefulness and fear and anxiety because of the pattern of Nps and Npsr1 mRNA cerebral expression and owing to pioneering pharmacological and behavioural rodent studies." (PMID 34451877, 2021). "In line with this research, in our study the conditioning effect in explicit anxiety ratings was not only influenced by NPSR1 genotype but additionally by the amount of stressful life events." (PMID 23630477, 2013). "neuropeptide S (NPS) and its receptor NPSR1 act along the hypothalamic-pituitary-adrenal axis to modulate anxiety, fear responses, nociception and inflammation." (PMID 22216302, 2011). "NPSR1 is expressed in the brain, where it modulates anxiety and responses to stress, but also in other tissues and cell types including lymphocytes, the lungs, and the intestine, where it appears to be up-regulated in inflammation." (PMID 20179762, 2010). "The NPS/NPSR1 system can also rescue anxiety-related behaviours arising during drug withdrawal." (PMID 34451877, 2021). "NPSR1 gene expression is also dependent on external factors, e.g. individuals with the TT genotype were found to be highly sensitive to the development of depression and anxiety due to their malnourished status during their early phase of life." (PMID 33332443, 2020). "Importantly, a few rodent studies examined the effects of NPS and NPSR1 antagonists on emotional behaviours in rodents with innate pathological phenotypes (i.e., high or low anxiety-related behaviour, depression-like behaviour and fear deficits) or exposed to acute stress." (PMID 34451877, 2021). "NPS was identified as an endogenous ligand for the orphan G‐protein‐coupled receptor GPR154 (now NPSR1) and found to both increase wakefulness and reduce anxiety‐related behaviors in mice." (PMID 36036349, 2022). "Prominent phenotypes in knockout mouse models for NPSR1 and NPS include attenuated arousal, deficits in learning and memory including disrupted fear learning, and mildly increased anxiety." (PMID 33922620, 2021). "Unexpectedly, infusions of the NPSR1 antagonist SHA 68 into the BNST, another important part of the extended amygdala network regulating mood and anxiety, also produced anti-depressant-like effects." (PMID 33922620, 2021). "NPSR1 has different physiological roles like modifying eating habits, release of adrenocorticotropic hormone (ACTH), suppressing anxiety, fear, panic, and sleep regulation." (PMID 33332443, 2020).
Anxiety (continued). "Additionally, polymorphisms in the neuropeptide S receptor (NPSR1), neuropeptide Y receptor (NPYR), and corticotropin-releasing hormone receptor (CRHR1) genes with individuals exposed to catastrophic events such as a hurricane or early trauma are more susceptible to GAD and anxiety sensitivity." (PMID 31633064, 2019). "NPSR1 is a member of the G-protein-coupled receptor binding neuropeptide S (NPS) and plays a role in arousal and anxiety-like behaviors." (PMID 29770110, 2018). "The Nps precursor deficient mice displayed deficits in exploration and increased anxiety-related behavior while Npsr1 knockout mice showed no significant impact on either locomotion or anxiety-related behavior." (PMID 37322045, 2023). "The knockout of the NPS precursor peptide produced significant deficits in exploration and increased anxiety-related behaviour in mice, whereas the knockout of the NPSR1 had no major impact on locomotion and anxiety-related behaviour." (PMID 34451877, 2021). "For anxiety ratings correlation analyses were conducted separately for each NPSR1 genotype group (T+, AA), irrespective of the 5HTTLPR genotype because it had no influence on rating data." (PMID 23630477, 2013).
panic disorder (12 papers, 2011 to 2024). An anxiety disorder characterized by multiple unexpected panic attacks with persistent concern of recurring attacks. "It should also be noted that male-specific associations of NPSR1 rs324981 genotypes with panic disorder or stress responsiveness have been reported, suggesting sex-specific functions of the NPS system." (PMID 34065431, 2021). "Polymorphisms in the NPSR1 gene have been linked with panic disorders, asthma, inflammatory bowel disease (IBD), and rheumatoid arthritis." (PMID 33332443, 2020). "In human studies, it has been shown that a single-nucleotide polymorphism (A>T) of the NPSR1 gene (rs324981) that codes for an amino acid exchange at position 107 (A107I) is more frequent in panic disorder patients." (PMID 25714705, 2015). "Genetic variations of the human NPS receptor (NPSR1) have been associated with pathologies like panic disorders." (PMID 25714705, 2015). "Human studies have linked the NPS system and single-nucleotide polymorphisms in the NPSR1 gene to diseases like asthma and allergy, inflammatory bowel disease, rheumatoid arthritis and panic disorders." (PMID 25714705, 2015). "The T allele of NPSR1 SNP is associated with panic disorder and elevated heart rate." (PMID 39025836, 2024). "In the meanwhile, we learned from other studies that the NPS precursor is coexpressed with glutamate in the brainstem, and a corresponding NPSR1 gene variation showed that NPSR potentially modulates glutamatergic activity in the ACC to increase the risk for panic disorder." (PMID 32104195, 2020). "Secondly, disease-specific genetic associations between 5HTTLPR and PTSD and between NPSR1 and panic disorder were reported." (PMID 23630477, 2013).
inflammatory bowel disease (9 papers, 2010 to 2021). A spectrum of small and large bowel inflammatory diseases of unknown etiology. "Several studies explored and found in carriers of genetic alterations of the NPSR1 an increased susceptibility to inflammatory bowel diseases (IBD) and lower gastrointestinal motility measurements, leading to perturbed gut functions." (PMID 33810221, 2021). "In addition, NPSR1 SNPs have shown genetic associations with other inflammatory phenotypes such as inflammatory bowel disease, and rheumatoid arthritis." (PMID 23565190, 2013).
anxiety disorder (8 papers, 2013 to 2024). A category of psychiatric disorders which are characterized by anxious feelings or fear often accompanied by physical symptoms associated with anxiety. "Even though spider phobia is a prototypical anxiety disorder, there is a research gap regarding its association with NPSR1 variants." (PMID 39167471, 2024). "However, another study revealed no genetic association of NPSR1 alleles with schizophrenia (and ADHD), suggesting a rather specific relationship of NPSR1 with anxiety disorders." (PMID 35741653, 2022). "Given the relevance of the neuropeptide S system in fear processing, we investigated a possible association of the functional NPSR1 rs324981 gene variant with neural correlates of sustained, phasic fear, and symptom reduction in a prototypical anxiety disorder not investigated yet." (PMID 39167471, 2024). "NPS/NPSR1 activity could potentially be useful in the therapy of various anxiety disorders." (PMID 35741653, 2022). "NPS/NPSR1 activity could potentially be useful in the treatment of various anxiety disorders." (PMID 36142912, 2022). "Some behaviours modulated by the NPS/NPSR1 system (as reviewed here in Section 2 and Section 3) are affected in some stress-related disorders (e.g., PTSD, MDD and anxiety disorders)." (PMID 34451877, 2021).
neuroblastoma (4 papers, 2011 to 2017). Neuroblastoma (NB) is the most common solid, extracranial childhood tumor. "Human SH-SY5Y neuroblastoma cells over-expressing NPSR1 were stimulated with 100 nM NPS for 0–24 h and the mRNA expression of RORA was measured using real-time PCR." (PMID 23565190, 2013). "Because NPSR1 is expressed in neuroendocrine tissues, we used SH-SY5Y neuroblastoma cells of neuroendocrine origin to validate the changes in gene expression observed in HEK293 cells." (PMID 28463995, 2017). "To characterize signaling pathways affected by NPS/NPSR1, we analyzed the effects of NPS on the global gene expression pattern of a human SH-SY5Y neuroblastoma cell line which overexpresses NPSR1-A and is of neuroendocrine origin." (PMID 24915894, 2014).
rheumatoid arthritis (4 papers, 2010 to 2013). A chronic, systemic autoimmune disorder characterized by inflammation in the synovial membranes and articular surfaces. "Using a candidate gene approach, we tested here for the first time the NPSR1 gene for association with rheumatoid arthritis, and genotyped 19 NPSR1 SNPs in a large cohort of 1808 RA patients and 888 controls from Sweden." (PMID 20179762, 2010). "From the Epidemiological Investigation of Rheumatoid Arthritis (EIRA) case-control study, 1,888 rheumatoid arthritis patients and 888 controls were genotyped for 19 single-nucleotide polymorphisms (SNPs) spanning the entire NPSR1 gene and 220 KB of DNA on chromosome 7p14." (PMID 20179762, 2010). "We sought to determine whether genetic variability at the NPSR1 locus influences the susceptibility and clinical manifestation of rheumatoid arthritis (RA)." (PMID 20179762, 2010). "Here, using a candidate gene approach, we sought to determine whether genetic variation at the NPSR1 locus influences individual predisposition to rheumatoid arthritis." (PMID 20179762, 2010). "Association between NPSR1 SNPs and rheumatoid arthritis in ACPA-negative patients vs controls." (PMID 20179762, 2010). "To test the potential contribution of the NPSR1 locus to rheumatoid arthritis, we initially compared the allelic frequencies of each genotyped SNP in EIRA cases (n = 1808) and controls (n = 888)." (PMID 20179762, 2010). "Association between NPSR1 SNPs and DAS28 in rheumatoid arthritis patients." (PMID 20179762, 2010).
schizophrenia (4 papers, 2012 to 2022). A major psychotic disorder characterized by abnormalities in the perception or expression of reality. "A case–control comparison revealed that the low-functioning NPSR1 Asn107 variant was significantly associated with schizophrenia." (PMID 35741653, 2022). "Genetic variants of NPSR1 were also investigated for a link with schizophrenia." (PMID 34065431, 2021). "Behavioral and physiological effects of NPS have been investigated in several preclinical animal models of psychosis-related behaviors, and two genetic association studies have investigated a possible link between NPS receptor (NPSR1) variants with schizophrenia in humans." (PMID 34065431, 2021). "There are only preliminary data on the relationship between the NPS/NPSR1 system and the course of schizophrenia." (PMID 35741653, 2022). "We found dysregulation of multiple transcripts whose human orthologs are associated with BPD and other psychiatric disorders including schizophrenia and ADHD, including: Epor, Smarca4, Cmklr1, Cat, Tac1, Npsr1, Fhit, and P2rx7." (PMID 22675514, 2012). "These animal results suggest that anti-psychotics may work by affecting peptidergic signaling; however, they do not provide answers about the real impact of the NPS/NPSR1 system on schizophrenia." (PMID 35741653, 2022). "However, they do not provide answers about the real impact of the NPS/NPSR1 system on schizophrenia." (PMID 36142912, 2022).
allergic asthma (3 papers, 2013 to 2016). A asthma with a basis in a pathological type I hypersensitivity reaction. "For example, the promoter methylation level of NPSR1 showed small but significant differences for persons suffering from severe adult or allergic asthma in children." (PMID 27602172, 2016). "NPSR1, normally highly methylated (>75 %), was hypomethylated by −3.29 and −1.40 % for severe adult asthma and allergic asthma in children, respectively." (PMID 27602172, 2016). "To further support an effect between DNA methylation in NPSR1 and allergic asthma, we saw an increase in DNA methylation related to blood sampling during the months July to December compared to January to March in both asthmatic and healthy children." (PMID 23372674, 2013). "We found that DNA methylation in the predicted NPSR1 promoter was slightly lower in peripheral blood from children that have allergic asthma as compared to healthy children." (PMID 23372674, 2013). "Interestingly, a previous report from the BAMSE birth cohort found a dose-response relation between exposure to parental smoking in infancy and IgE sensitisation, supporting a link between variations in NPSR1 methylation and allergic asthma." (PMID 23372674, 2013).
childhood asthma (3 papers, 2013 to 2021). "The role of NPSR1 in childhood asthma is also indicated by higher levels of NPSR1 protein in the plasma of children with mild intermittent asthma compared to healthy controls." (PMID 34948451, 2021). "We conclude that RORA SNPs are associated with childhood asthma and show epistasis with NPSR1, and the interaction between RORA and NPSR1 may be of biological relevance." (PMID 23565190, 2013).
endometriosis (3 papers, 2022 to 2025). The growth of functional endometrial tissue in anatomic sites outside the uterine body. "Recently, DNA sequencing studies have found that deleterious coding variants within the gene NPSR1 were overrepresented in individuals with endometriosis; a finding that was replicated in a population of rhesus macaques with spontaneous endometriosis." (PMID 39859296, 2025). "The study showed that deleterious low-frequency coding variants in NPSR1 are more common in patients with familial endometriosis, particularly in moderate to severe stages." (PMID 39062866, 2024). "This study showed that deleterious low-frequency coding variants in NPSR1 are overrepresented in patients with familial endometriosis, especially in moderate/severe stages." (PMID 36358904, 2022). "Variants in the NPSR1 gene could thus potentially influence inflammation and the perception of pain symptoms in endometriosis patients." (PMID 39062866, 2024). "Although the precise mechanisms by which NPSR1 might contribute to endometriosis remain to be defined, known functions of NPSR1 that may be particularly relevant to endometriosis include the regulation of immune responses and inflammation and the modulation of pain perception." (PMID 39062866, 2024). "While those genes have not yet been validated as potential targets for endometriosis treatment, a recent study has identified and validated a gene named Neuropeptide S receptor 1 (NPSR1) as a potential target through DNA sequencing." (PMID 36358904, 2022). "Overall, these studies suggest that NPSR1 is a nonhormonal target in endometriosis." (PMID 39062866, 2024).
neuroendocrine tumors (3 papers, 2014 to 2021). "In this study, we investigated whether NPS or NPSR1 might be used as biomarker for NET in a wide panel of neuroendocrine tumors, characterized by assessing the Ki-67 proliferation index and chromogranin-A and synaptophysin expression." (PMID 24915894, 2014). "To evaluate whether NPS/NPSR1 might be used as markers for certain NETs, we studied the expression of NPS and NPSR1 in neuroendocrine tumors from different organs." (PMID 24915894, 2014). "Because the NPS/NPSR1 system acts on the hypothalamic–pituitary–adrenal (HPA) axis to affect stress response and has direct and indirect effects on immunity, we hypothesized that NPSR1 may have important effects on neuroendocrine neoplasms." (PMID 24915894, 2014). "In addition, a previous study suggested that NPSR1 is a marker widely expressed in neuroendocrine tumors (NET) with the exception of adrenal pheochromocytomas, the stimulation of NPSR1 with NPS results in activation of pathways that are relevant for cancer development." (PMID 34017995, 2021). "Our aim was to study whether NPS/NPSR1 could be used as a biomarker for neuroendocrine neoplasms and to identify the gene pathways affected by NPS/NPSR1." (PMID 24915894, 2014).
adrenal pheochromocytomas (2 papers, 2014 to 2021). "In conclusion, NPSR1 is a marker widely expressed in NET with the exception of adrenal pheochromocytomas." (PMID 24915894, 2014). "NPSR1 and NPS were expressed in most NET tissues, with the exception of adrenal pheochromocytomas in which NPS/NPSR1 immunoreactivity was very low." (PMID 24915894, 2014).
alcohol use disorder (2 papers, 2022). "Genetic variants of NPSR1 in humans, such as the functional polymorphism p (Asn107lle) (rs324981, A>T), have a significant effect on alcohol consumption and risk of alcohol use disorder, effects that can be modified by sex, age and environmental factors." (PMID 36263121, 2022).
Obesity (2 papers, 2020 to 2021). Accumulation of substantial excess body fat. "The analyses of NPSR1 rs324981 (A>T) polymorphism find a significant association with obesity in Dominant genetic models (AA Genotype vs AT + TT Genotype)." (PMID 33332443, 2020). "NPS concentrations were significantly (p = 0.000) moderated by NPSR1 gene Asn107Ile polymorphism with increasing obesity." (PMID 33332443, 2020). "We believe that large scale polymorphism data of population for important gene players including NPSR1 will be more useful to understand obesity and its associated risk factors." (PMID 33332443, 2020). "The current investigation explores the possible association of NPSR1 Asn107Ile variant with NPS serum levels and the NPS-NPSR1 interaction through molecular simulation analysis in obesity." (PMID 33332443, 2020). "This study is first to report the significant association of NPSR1 (Asn107Ile rs324981) polymorphism with obesity in the Pakistani obese male individuals." (PMID 33332443, 2020). "Our results NPSR1 A/T polymorphisms provides further supportive evidence in the association of obesity." (PMID 33332443, 2020). "Furthermore, NPSR1 Asn107Ile variant (AT+TT) genotype distribution was found to be associated with obesity in the Pakistani population." (PMID 33332443, 2020). "Moreover, previous experimental studies data suggest the decreased activation of NPSR1-NPS signaling can lead to obesity." (PMID 33332443, 2020).